CTHRC1 (collagen triple helix repeat containing 1)
Diseases named in the same sentence as CTHRC1 in open-access papers (continued):
Sharing a sentence is not in itself a finding about the gene and the disease.
cancer (continued). "The nude mice injected with SKOV3luc-Lenti-CTHRC1 cells developed less peritoneal metastases after using PF-228, which further confirmed that CTHRC1 induced cancer metastasis through activating the phosphorylation of FAK." (PMID 29021002, 2017). "Simultaneously, we revealed that the expression of CTHRC1 was associated with FIGO stage, lymph node metastasis, ascites-derived cancer cells and distance metastasis in EOC." (PMID 29021002, 2017). "Recent studies have demonstrated that CTHRC1 is involved in cell adhesion and motility of various carcinomas." (PMID 29021002, 2017). "Immunohistochemical analysis of various human primary cancers and metastases has revealed that CTHRC1 expression is actually limited to the stromal cells of solid tumors." (PMID 27430622, 2016). "Overexpression of Cthrc1 transgene promoted migration of cells from several lineages, including primary mouse embryonic fibroblasts, smooth muscle and cancer cells." (PMID 27430622, 2016). "Collagen triple helix repeat-containing 1 (CTHRC1) is aberrantly overexpressed in multiple malignant tumors." (PMID 26452130, 2015). "Aberrant CTHRC1 expression is detected in several malignant tumors, including melanoma, and cancers of the gastrointestinal tract, esophagus, breast, ovary, thyroid, liver and pancreas." (PMID 26452130, 2015). "Our inability to detect Cthrc1 in the parenchyma of tissues prompted us to investigate Cthrc1 expression in various human cancers by immunohistochemistry using rabbit monoclonal anti-Cthrc1 Vli-55." (PMID 24945147, 2014). "Increased Cthrc1 expression has been reported in many cancer cells using a variety of commercially available polyclonal antibodies, however, most of them lack rigorous characterization with respect to specificity in immunohistochemistry applications." (PMID 24945147, 2014). "Microarray analyses have identified Cthrc1 as a gene overexpressed in many cancers with reports of Cthrc1 localization in cancer cells as determined by immunohistochemistry." (PMID 24945147, 2014). "Many of the studies reporting Cthrc1 overexpression in cancers relied on microarray expression data and insufficiently characterized antibodies." (PMID 24945147, 2014). "Future work with a focus on oncology patients is required for a more in-depth investigation of Cthrc1 levels in cancer patients." (PMID 24945147, 2014). "Ectopic up-regulation of CTHRC1 in cancer cells resulted in elevated invasive and proliferative abilities, which were attenuated by the specific CTHRC1 siRNA." (PMID 25238260, 2014). "We propose that CTHRC1 promotes cancer cell invasiveness through activation of ERK and subsequent induction of MMP9 expression." (PMID 24504172, 2014). "CTHRC1 promoted adhesion of cancer cells to extracellular matrix through induction of integrin β1 expression and activation of focal adhesion kinase." (PMID 23922981, 2013). "In another study, it was shown that the CTHRC1 expression was dramatically up-regulated in several cancer types including CRC." (PMID 22321245, 2012). "Aberrant expression of CTHRC1 has recently been reported in human solid tumors, including cancers of the gastrointestinal tract, lung, breast, thyroid, ovarian, cervix, liver, and the pancreas." (PMID 17389037, 2007). "Here, we performed an integrative multi-omics analysis across seven digestive cancer types and identified a conserved four-gene signature-DCN, COL10A1, CTHRC1, and TREM2-that is consistently enriched in matrix cancer-associated fibroblasts (mCAFs) and myeloid cells." (PMID 41977392, 2026). "Notably, genes such as ANO3 and CTHRC1 emerged as novel contributors to pan-cancer metastasis, with their expression levels showing a direct correlation." (PMID 39748426, 2025). "In conclusion, abnormal expression of CTHRC1 is observed in a variety of human solid tumors and may be closely related to the malignancy and invasion of cancer tissues." (PMID 40898459, 2025).
cancer (continued). "Through a comprehensive discussion of CTHRC1's diverse functions, we aim to provide insights that could pave the way for innovative approaches in cancer therapy." (PMID 40201173, 2025). "CTHRC1 has been reported to play critical roles in various human cancers." (PMID 39052013, 2024). "While exposure to WT-BMDM CM alone induced the expression of several myMAF and vMAF genes, the combination of CM from both WT-BMDMs and cancer cells amplified the induction of Cthrc1, Spp1, and Postn, while suppressing several vMAF genes, indicating an induction of a myMAF phenotype." (PMID 38678021, 2024). "However, the deeper mechanisms and functions of the CTHRC1 network in these cancers require further study." (PMID 39052013, 2024). "Notwithstanding, Cthrc1 also supports migration and adhesion activities of certain cancer cells." (PMID 37932771, 2023). "CTHRC-1 promotes cell migration and invasion in both cancers." (PMID 36982551, 2023). "Notably, CTHRC1 was removed from the PSC-conditioned media to exclude interference from CTHRC1 on cancer cell migration/invasion." (PMID 37444482, 2023). "Periostin (coded by the POSTN gene) has a central role in the CTHRC1–PSCs–cancer metastasis axis." (PMID 37444482, 2023). "Further refinement of this matrix risk signature to specifically predict which lesions will progress to cancer identified a minimum 6-gene risk signature of RSPO1, CTHRC1, SPP1, MMRN1, COL10A1, and PRG4 as the most significant matrisomal predictors of premalignant progression with a ROC AUC of 0.99." (PMID 36404344, 2022). "Could the CTHRC1-POSTN connect be of significance to their role as part of the matrisome in cancers remains to be tested experimentally." (PMID 36190948, 2022). "Differential gene expression analysis of these cancers to identify genes with a 2-fold change (increase/decrease) in 3 or more cancers led us to 19 matrisome genes that could work with CTHRC1." (PMID 36190948, 2022). "Many studies reported that CTHRC1 is regulated by miRNA in various cancers, therefore upstream miRNAs that may target CTHRC1 were predicted via many databases." (PMID 35313900, 2022). "The cross-linking of collagen fibers controls their density and packing order which could regulate ECM stiffness to further drive cancer progression downstream of CTHRC1." (PMID 36190948, 2022). "In conclusion, it was disclosed in this study that CTHRC1 worked as a cancer promoter in LUAD, and miR-30a-5p could target and downregulate CTHRC1 to regulate cell adhesion, and inhibited LUAD cell invasion and migration." (PMID 35313900, 2022). "Studies revealed that CTHRC1 is regulated by miRNAs in cancers." (PMID 35313900, 2022). "Our study in evaluating 1027 matrisome genes across cancers, has identified a novel set of genes (MMP13, FNDC1, SFRP4 and ADAMTS16) that could work with CTHRC1 to regulate cancer progression." (PMID 36190948, 2022). "Together they further emphasize the possible role overexpression of these matrisome genes and their crosstalk as part of a regulatory and/or functional network could have in driving the impact of the ECM through CTHRC1 in cancers." (PMID 36190948, 2022). "CTHRC1 genetic alterations in other cancer types require further exploration." (PMID 34702252, 2021). "Thus, the pattern of correlations between CTHRC1 expression and immune cell infiltration was distinctly distinguished across cancers." (PMID 34702252, 2021). "CTHRC1 is a crucial oncogene that may represent an important target for the effective treatment of cancers." (PMID 34702252, 2021). "High CTHRC1 expression levels were associated with shorter OS and DFS across cancers." (PMID 34702252, 2021). "In addition, a potential correlation between CTHRC1 genetic alterations and the clinical survival prognosis of patients in pan-cancer samples was also detected." (PMID 34702252, 2021). "Therefore the next part of our study will mainly focus on the unique role of CTHRC1 in these six types of human cancers." (PMID 34615943, 2021).
cancer (continued). "Additionally, the relationship between the CTHRC1 expression level and various cancer pathological stages was analyzed using GEPIA2." (PMID 34702252, 2021). "However, to the best of our knowledge, CTHRC1 dysregulation and its impact on the various other subtypes of cancer is yet to uncover." (PMID 34615943, 2021). "Furthermore, CTHRC1 promoter methylation level and OS information have also proven its useful values as a novel potential biomarker of these cancers." (PMID 34615943, 2021). "CTHRC1 is overexpressed in various cancer types and functions as an important oncogene that may promote tumorigenesis and development through different mechanisms." (PMID 34702252, 2021). "In addition, CTHRC1 mRNA expression was also positively correlated with the stages of certain cancers like ACC, ESCA, KIRC, BLCA, etc.." (PMID 34702252, 2021). "We attempted to investigate the role of CTHRC1 in human cancers." (PMID 34702252, 2021). "Inhibiting CTHRC1 can isolate cancer cells from spreading to nearby organs." (PMID 32848510, 2020). "These properties' pathways affected by CTHRC1 play an essential role not only in tissue remodeling after injury, regulation of ossification, and other physiological processes but also in the development of cancer and metastasis." (PMID 32848510, 2020). "Therefore, we used TIMER to analyze the correlation of CTHRC1 level with immune infiltration levels in various cancer types." (PMID 33628726, 2020). "However, little is known about the regulation and function of CTHRC1 in the cancer microenvironment." (PMID 31798347, 2019). "Collagen triple helix repeat containing (CTHRC1), which was identified as a cancer‐related factor, is a promigratory protein involved in multiple processes, including vascular remodeling, antifibrosis, metabolism, bone formation, and cancer." (PMID 30302922, 2018). "Similarly, PCR was used to evaluate CTHRC1 mRNA levels in cancer samples in 20 pairs of primary CRC tissues and adjacent colorectal mucosa samples (P < 0.001)." (PMID 30302922, 2018). "CTHRC1 promotes cancer progression and activates relevant signalling molecules, which urged us to determine whether CTHRC1 plays a similar role in determining the aggressiveness of NSCLC." (PMID 29631554, 2018). "Then, we investigated whether CTHRC1 could promote cancer cell migration and invasion through the EMT process in CRC cells." (PMID 30302922, 2018). "CTHRC1 is aberrantly over-expressed in multiple malignant tumors." (PMID 29021002, 2017). "Moreover, the inhibition of CTHRC1 using siRNA has been described as potential therapeutic strategy for cancer progression." (PMID 28427201, 2017). "Previous studies showed overexpression of CTHRC1 in melanoma and cancers of many other organs." (PMID 29285247, 2017). "Although CTHRC1 expression has been observed in human solid cancers, the molecular mechanisms underlying CTHRC1 actions in cancer cells is still not entirely clear." (PMID 29021002, 2017). "Additionally, the protein level of CTHRC1 was lower in the para-carcinoma tissues than in the carcinoma tissues." (PMID 29234238, 2017). "In addition, we found upregulation of several genes such as HMGA2, CTHRC1 (top two genes) whose role in cancer progression and survival is well established." (PMID 27144525, 2016). "CTHRC1 was first reported as a novel secretory protein in injured and diseased arteries, and it is thought that CTHRC1 may act to inhibit collagen expression and promotes cell migration, both of which are essential functions for an invasive cancer." (PMID 26252227, 2015). "Previous studies report CTHRC1 overexpression as a poor survival factor in many cancers, but its prognostic role in EOC is unknown." (PMID 26452130, 2015). "With Cthrc1 expression in wound healing and cancers originating from activated stromal cells we wanted to determine whether Cthrc1 expressed by these cells can account for circulating levels with potential systemic effects." (PMID 24945147, 2014).
cancer (continued). "Therefore, it is possible that CTHRC1 plays a certain role in the early stage of carcinogenesis of several cancers, including HCC." (PMID 24841500, 2014). "An increasing number of studies report that Cthrc1 is expressed in various cancer cells." (PMID 24945147, 2014). "Insight into the pro-metastatic role of CTHRC1 may open a new avenue for the development of cancer therapies designed to inhibit metastasis." (PMID 24504172, 2014). "However, further exploration is needed to explain how CTHRC1 regulates cancer migration and invasiveness." (PMID 25238260, 2014). "Furthermore, we used immunohistochemistry performed with rabbit monoclonal antibodies to localize Cthrc1 in various human cancers previously reported to overexpress Cthrc1." (PMID 24945147, 2014). "Hence, by secreting CTHRC1 into its microenviroment, cancer cells stimulate their own motility and that of adjacent cancer cells by activating RhoA signaling." (PMID 23922981, 2013). "In this study we report two candidate genes, asporin (ASPN) and collagen triple helix repeat containing 1 (CTHRC1), which might be significant in mammary gland carcinogenesis and may also be important either in cancer diagnosis or therapy." (PMID 17389037, 2007). "Based on this result, CTHRC1 alterations may be involved in cancer progression." (PMID 34702252, 2021). "Therefore, follow-ups of functional mechanisms of CTHRC1 in cancers is worth further investigating." (PMID 34702252, 2021). "CTHRC1 may represent an important therapeutic target for human cancers." (PMID 34702252, 2021). "Via KM plotter tool, next, we investigated whether CTHRC1 higher transcriptional level was associated with the OS duration of the cancer patients or not." (PMID 34615943, 2021). "As a participant in tissue remodeling or immune response, CTHRC1 may promote early-stage cancer." (PMID 32848510, 2020). "Therefore, CTHRC1 is suggested to play an essential role in cancer progression." (PMID 33628726, 2020). "However, the paracrine effect of osteoclast-secreted CTHRC1 in cancer-induced bone lesion development is unknown." (PMID 30469488, 2018). "CTHRC1 was then found to be ubiquitously expressed in numerous cell types such as fibroblasts and smooth muscle cells, and aberrantly up-regulated in several malignant tumors, including melanoma, and cancers of gastrointestinal tract, liver, lung, ovary and so on." (PMID 28697793, 2017). "Therefore, methylation of the CpG site involved in regulating CTHRC1 may vary in different types of cancer." (PMID 28645305, 2017). "Transcriptional induction and post-translational stabilization of FRA-1 via MEK/ERK signalling increases the abundance of FRA-1, which has been causally linked to more aggressive behaviours of multiple cancer cell types, but not through a CTHRC1-dependent pathway." (PMID 28645305, 2017). "To date, how CTHRC1 promotes cancer cell migration and adhesion remains unclear." (PMID 26452130, 2015). "So we speculated that cancer cells secrete CTHRC1 to promote their migration." (PMID 23922981, 2013). "Our results extend these implications to PDAC, highlighting the importance of the spatially correlated crosstalk between CTHRC1+GREM1+ myCAF and SPP1+APOE+ TAM that drive fibrosis, immunosuppression, and EMT in PDAC and potentially other cancers." (PMID 39075108, 2024). "A CAF subpopulation which highly expressed extracellular matrix (ECM) remodeling genes (MMP11, CTHRC1 and COL1A2) was annotated as matrix CAF (mCAF), resemble the previously reported mCAFs in cancer data." (PMID 39703515, 2024). "Of these genes, CTHRC1, PDGFA, and IL7 were also shortlisted as matrisome genes of interest in the pan-cancer analysis." (PMID 36190948, 2022). "In terms of mechanism, several studies have found that CVBD, through the CTHRC1-AKT/ERK-Snail pathway or EGFR-FAK-AKT/ERK1/2-Slug pathway, inhibit cancer tumorigenesis through CVBD inducing mitochondrial apoptosis in cancer cells." (PMID 33816313, 2021).
cancer (continued). "In this way, MALAT1 influences proliferation, invasion and migration of cancer cells through regulation of multitudinous known downstream genes, including several metastasis-related genes (CCT4/CTHRC1/ROBO1/MIA2) and cell cycle control genes (p21/p27/B-MYB)." (PMID 31792655, 2020). "Consistent with this, we found that knockdown of CTHRC1 attenuated ERK activation and cancer cell invasivity." (PMID 24504172, 2014). "Collagen triple helix repeat-containing 1 (CTHRC1), a novel oncogene, was identified to be aberrantly overexpressed in several malignant tumors." (PMID 25238260, 2014). "Periostin (POSTN) and CTHRC1 are extracellular matrix (matricellular) proteins that contribute to progression in multiple human cancer types but have not been studied in MPNST." (PMID 39511408, 2025). "β-catenin binds transducin beta-like protein 1 (TBL1/TBLR1), and this complex stimulates the expression of several Wnt/APC/β-catenin pathway target genes, including proliferative factors, such as S100A4 or collagen triple helix repeat containing-1 (CTHRC1), identified as cancer-related proteins." (PMID 35913675, 2023). "Although the anti-CTHRC1 antibody is known as a non-cytotoxic agent, the antibody clearly worked through reducing cancer proliferation and ECM formation." (PMID 37444482, 2023). "We speculate that, although CTHRC1 is an important multi-functional regulatory molecule in the TME, its regulatory effects on cancer cell migration/invasion are largely dependent on the POSTN expression of PSCs." (PMID 37444482, 2023). "Of the 9 cancers shortlisted in the pan-cancer analysis based on CTHRC1 overexpression and its effect on cancer survival, BRCA, HNSC and LIHC were also shortlisted in the individual cancer study based on their CTHRC1 expression and its effect on survival." (PMID 36190948, 2022). "Taken together, the multivariate analysis across CTHRC1 overexpressing cancers does not reveal any distinctly conserved effect on survival across race or gender." (PMID 36190948, 2022). "Moreover, high CTHRC1 expression declined the adhesive ability of LUAD cells, which promoted cancer cell invasion and metastasis." (PMID 35313900, 2022). "Notably, the expression of CTHRC1 was positively correlated with ICP gene CD276, which was identified a promising therapeutic target for malignant tumors." (PMID 34702252, 2021). "Our results revealed that CTHRC1 was genetically altered in only 4%, 0.6%, 9%, 4%, 5%, and 6% of the queued HNSC, KIRC, LIHC, LUAD, STAD, and UCEC samples, respectively, and deep amplification genetic abnormality was most frequent in these cancer subtypes." (PMID 34615943, 2021). "Six genes (SLCO2A1, MGAT4B, SLC25A33, MCCC1, OIP5, and CTHRC1) have been shown to affect the tumorigenesis of other cancer types but not PC." (PMID 30024105, 2018). "Consistent with MACE results, CTHRC1, TCF4 and ZEB1 were significantly higher expressed in PDAC compared to normal pancreas tissues, with median normalized Ct (ΔCt) values between −1.8 and 1.8 in cancer- and 3.1-5.1 in normal tissues." (PMID 25910082, 2015). "In summary, we report here that Cthrc1 is a marker for activated stromal cells and Cthrc1 expression was not detectable in the cancer cells." (PMID 24945147, 2014). "In addition, our data add the information that CTHRC1 protein is actually expressed in human HCC tissues, more prominently in cancer cells which are supposed to be aggressive." (PMID 24841500, 2014). "SPP1, CTHRC1 and GREM1 are candidate biomarkers to identify the cancer." (PMID 24299561, 2013). "Nevertheless, we found that neutralizing CTHRC1 completely reversed the activation of PSCs (migration/invasion/ECM secretion) and dramatically hindered the differentiation of PSCs to myCAFs, as well as blocked the pro-tumoral effects mediated by activated PSCs (e.g., cancer proliferation)." (PMID 37444482, 2023). "CTHRC1 secretion in the cancer cell lines was not influenced by periostin treatment either." (PMID 37444482, 2023).